GDNF (glial cell derived neurotrophic factor)
Diseases named in the same sentence as GDNF in open-access papers (continued):
Sharing a sentence is not in itself a finding about the gene and the disease.
manic episode (1 paper, 2020). "In order to reveal this point, we kept cortisol level, BMI and age under control statistically in the groups and we found that GDNF and Nrn 1 levels were significantly lower while IGF-1 levels were significantly higher in bipolar manic episode patients compared to the control group." (PMID 32283906, 2020).
metabolic syndrome (1 paper, 2022). A cluster of metabolic risk factors for CARDIOVASCULAR DISEASES and TYPE 2 DIABETES MELLITUS. "Mentioned reports suggest GDNF has a protective role against the development of major components of the metabolic syndrome." (PMID 35769087, 2022). "Like BDNF, GDNF signs in the suggested metabotropic hypothesis of metabolic syndrome." (PMID 35769087, 2022).
muscular dystrophy (1 paper, 2020). Muscular dystrophy (MD) refers to a group of more than 30 genetic diseases characterized by progressive weakness and degeneration of the skeletal muscles that control movement. "Furthermore, GDNF is upregulated following increased physical activity in rats and in disease models of muscular dystrophy and polymyocitis." (PMID 33036659, 2020).
neuroendocrine tumors (1 paper, 2022). "LIF may be utilized for signaling mediated by GDNF and may be important in the pathobiology of neuroendocrine tumors." (PMID 35311096, 2022).
optic neuropathies (1 paper, 2021). "Because optic neuropathies such as glaucoma are slowly progressing neurodegenerative disorders, we next analysed whether the synergistic rescue effect of GDNF and CNTF is long-lasting." (PMID 34827174, 2021).
oral cancer (1 paper, 2025). "GDNF expression is significantly elevated in oral cancer tissues, and GDNF treatment enhances the phosphorylation of extracellular signal-regulated kinases (ERK), p38, and JNK, which increases the DNA-binding activity of AP-1 and increases the expression of matrix metalloproteinases (MMPs)." (PMID 40421086, 2025).
ovarian dysfunction (1 paper, 2022). The inability of the ovaries to function. "In contrast, PDGF and GDNF contents in the follicular fluid of patients with ovarian dysfunction (such as DOR and aging) were lower than those in young people with normal ovarian functions." (PMID 35784529, 2022).
overnutrition (1 paper, 2019). An imbalanced nutritional status resulting from excessive intake of nutrients. "Moreover, neurotrophic factors as BDNF, ciliary neurotrophic factor (CNTF), and glial cell-derived neurotrophic factor (GDNF) regulate adult neurogenesis in multiple stages of NSC maturation and their expression is affected by overnutrition and metabolic stress." (PMID 31417349, 2019).
parasitic infections (1 paper, 2022). "Their findings indicate that GDNF was present in infected rat macrophages, suggesting that GDNF may be involved in the response to parasitic infections of the intestine." (PMID 36558772, 2022).
pericarditis (1 paper, 2026). An inflammatory process affecting the pericardium. "Among them, elevated levels of NEU1, GDNF, and LAT increased the risk of pericarditis, whereas higher levels of CASP8, ZFYVE27, and NAPA decreased the risk of pericarditis." (PMID 41674924, 2026).
pituitary adenomas (1 paper, 2021).
Polydipsia (1 paper, 2022). Excessive thirst manifested by excessive fluid intake. "Therefore, analysis on how GDNF levels in the CSF relate to various parameters, such as dopamine metabolism, A2AR levels and ligand binding, coffee intake, avolition and polydipsia is an important future perspective." (PMID 35618883, 2022).
polymyositis (1 paper, 2024). A rare idiopathic inflammatory myopathy characterized by symmetric proximal muscle weakness and elevated muscle enzymes. "GDNF is known to be produced by muscle cells, is upregulated in the muscles of patients with polymyositis, Duchenne-type muscle dystrophy, and other neuromuscular diseases, and is considered a mediator of muscle pain in these pathological conditions." (PMID 38267849, 2024).
Pruritus (1 paper, 2023). Pruritus is an itch or a sensation that makes a person want to scratch. "Another mediator of pruritus in AD may be artemin which belongs to the glial cell line-derived neurotrophic factor (GDNF)." (PMID 37834183, 2023).
psychostimulant addiction (1 paper, 2023). "As a potent neurotrophic factor modulating the function of dopamine neurons, glial cell line-derived neurotrophic factor (GDNF) acting through its receptor RET on dopamine neurons may provide a novel therapeutic avenue towards psychostimulant addiction." (PMID 37238631, 2023).
pyelonephritis (1 paper, 2019). An inflammatory process affecting the kidney. "Serious TEAEs were reported for five (24%) GDNF patients and no placebo patients; all were unrelated to study medication: device-related events (three), pyelonephritis (one), complications from conus injury following a car accident (one)." (PMID 30808022, 2019).
renal failure (1 paper, 2023). "For example, ADMSC-Exos expressing glial cell line-derived neurotrophic factor (GDNF) reduced peritubular capillary thinning and renal failure, stimulated angiogenesis, cell migration, SIRT1 signaling pathway, and conferred apoptosis resistance." (PMID 36768406, 2023).
retinal detachment (1 paper, 2009). An eye emergency condition which may lead to blindness if left untreated. "Tractional retinal detachment, being a side effect of GDNF per se, seems unlikely since a gene therapy approach to GDNF delivery specifically revealed no such complications." (PMID 19461934, 2009).
retinoblastoma (1 paper, 2022). A malignant tumor that originates in the nuclear layer of the retina. "In conclusion, our results suggest that downregulation of miR-211-5p can promote carboplatin resistance in human retinoblastoma Y79 cells, and this process can promote GDNF expression." (PMID 35311096, 2022). "Our results suggest that downregulation of miR-211-5p promotes carboplatin resistance in human retinoblastoma Y79 cells, and this process can be affected by GDNF–LIF interaction." (PMID 35311096, 2022).
Rotavirus infection (1 paper, 2020). Infection with any of the rotaviruses. "In vitro, we did not observe increased GDNF expression in Caco-2 enterocytes during rotavirus infection, which may indicate the need for interaction with EGCs and glial cell-derived GDNF." (PMID 31964731, 2020). "Rotavirus infection stimulated GDNF expression in bystander cells of mouse duodenum." (PMID 31964731, 2020). "As rotavirus causes significant lesions in the small intestine but does not impair the intestinal barrier, and GSNO contributes to maintaining the epithelial barrier during rotavirus infection in Caco-2 cells, we next asked whether rotavirus infection could stimulate GDNF production in vivo." (PMID 31964731, 2020).
sarcoma (1 paper, 2018). A usually aggressive malignant neoplasm of the soft tissue or bone. "Moreover, glial cell line-derived neurotrophic factor (GDNF) utilizes the rat sarcoma (Ras)/ERK1/2 pathway to promote SSC proliferation." (PMID 29416712, 2018).
spasm (1 paper, 2019). "The results showed that BMP2 and GDNF expression was significantly decreased in the spasm segment compared with the normal colon and the distension segment." (PMID 31849612, 2019).
spinal disease (1 paper, 2025). "Notably, body mass index, smoking status, and diabetic status all negatively impacted GDNF protein levels, suggesting that lifestyle modification may represent an indirect means of preserving neurotrophic function in spinal disease." (PMID 40722606, 2025).
spinal stenosis (1 paper, 2025). Narrowing of the spinal canal. "A deeper understanding of the post-transcriptional control of GDNF may offer new diagnostic biomarkers and therapeutic targets for the management of spinal stenosis and related degenerative disorders." (PMID 40722606, 2025). "In this study, we focused on the expression profile of GDNF within ligamentum flavum tissue from patients with spinal stenosis." (PMID 40722606, 2025). "This study offers a novel exploration of the relationship between GDNF expression and lumbosacral spinal stenosis, an area that has not been extensively studied." (PMID 40722606, 2025).
squamous cell carcinoma of the lung (1 paper, 2018). "GDNF and TFAP2A have been reported to be highly methylated in squamous cell carcinoma of the lung and in adenocarcinoma, respectively." (PMID 29796116, 2018).
status epilepticus (1 paper, 2025). Status epilepticus is defined as a continuous seizure lasting more than 30 min, or two or more seizures without full recovery of consciousness between any of them. "We transplanted naïve immortalized human adipose-derived MSCs (Ctrl-MSCs) or GDNF-releasing MSCs (GDNF-MSCs, releasing 588.67 ± 20.14 pg/ml/24 h GDNF) into rat hippocampi after kainic acid-induced status epilepticus." (PMID 40839114, 2025).
stenosis (1 paper, 2025). "Such approaches could clarify how translational repression contributes to GDNF depletion in spinal stenosis and potentially reveal novel targets for therapeutic intervention." (PMID 40722606, 2025).
stress-related disorder (1 paper, 2021). Stress-related disorders are mental health disorders that are a result of an atypical response to both short and long-term anxiety due to physical, mental, or emotional stress. "BDNF, GDNF, and NGF are the most abundant neurotrophins that existed in CNS and involved in the pathophysiology of mood and other stress-related disorders (Bjorkholm & Monteggia 2016, Castren & Kojima 2017, von Bohlen Und Halbach & von Bohlen Und Halbach 2018)." (PMID 34605773, 2021).
tapeworm infection (1 paper, 2015). "Considering GDNF’s involvement in neuroprotection, neural restoration, survival and remodeling, smooth muscle alterations and the ENS plasticity (nerve distribution) observed in tapeworm infection, it is logical to assume a key role for GDNF in the response to parasitic neural alterations." (PMID 26635531, 2015).
temporal lobe epilepsy (1 paper, 2022). A localization-related (focal) form of epilepsy characterized by recurrent seizures that arise from foci within the temporal lobe, most commonly from its mesial aspect. "To address this question, we performed GDNF exposure experiments in human epileptic hippocampal slices from patients with drug-resistant temporal lobe epilepsy that underwent temporal lobe resection for therapeutic purposes." (PMID 36361981, 2022).
tic disorder (1 paper, 2018). Disorders characterized by recurrent TICS that may interfere with speech and other activities. "Serum NGF and GDNF levels were higher in females with tic disorder than males." (PMID 30190739, 2018). "Serum NGF and GDNF levels were higher in females with tic disorder than males in our study." (PMID 30190739, 2018). "Our study was perhaps the first study to investigate serum NGF and GDNF levels in tic disorder." (PMID 30190739, 2018). "The purpose of this study was to compare serum GDNF and NGF levels, demographic characteristics and clinical parameters between in patients with tic disorder and healthy controls." (PMID 30190739, 2018). "The aim of this study was to investigate serum Glial Cell Line-Derived Neurotrophic Factor (GDNF) and Nerve Growth Factor (NGF) levels in patients with tic disorder and healthy controls." (PMID 30190739, 2018). "The fact that NGF and GDNF levels were not correlated with tic disorders in our study does not exclude the role of neurotrophic factors in the etiopathogenesis of tic disorder." (PMID 30190739, 2018). "Unlike these results, GDNF levels were higher in women with tic disorder in our study." (PMID 30190739, 2018).
type 1 diabetes (1 paper, 2021). "In this section, encapsulation of glial cell line-derived neurotrophic factor (GDNF)-secreting human embryonic kidney (HEK) cells, islet cells as an alternative therapy to treat retinal degenerative disease, and type 1 diabetes will be illustrated." (PMID 34199641, 2021).
xerostomia (1 paper, 2020). Dryness of the mouth resulting from reduced salivary secretion. "Given these adverse associations between GFL members and cancer progression, it is essential to study in detail the effect of GDNF on HNSCC before its clinical testing in treating or preventing xerostomia." (PMID 32084217, 2020). "Our ultimate goal is to determine whether systemic administration of GDNF at high dose is safe for the management of hyposalivation or xerostomia in HNSCC patients." (PMID 32084217, 2020). "However, positive stromal protein expression of GDNF may be associated with a higher risk of relapse in certain patients, especially those with HPV-negative HNSCC; therefore, systemic administration of GDNF for the goal of xerostomia treatment is not recommended." (PMID 32084217, 2020).
ZIKV infection (1 paper, 2018). "As controls, we also measured levels of two other cytokines whose mRNA levels were not significantly affected by ZIKV infection; glial cell line-derived neurotrophic factor (GDNF) and Androgen-binding protein (ABP) following ZIKV infection of Sertoli cells." (PMID 29615760, 2018).
tumor (138 papers, 2007 to 2026). "It has been reported that tumor-associated macrophages (TAMs), a pro-tumor M2 subtype of macrophage, express more GDNF than resting macrophages." (PMID 37610689, 2024). "Tumor-associated macrophages (TAMs), a pro-tumor M2 subtype of macrophage, release GDNF, contributing to NI promotion." (PMID 39766161, 2024). "Further analysis suggested that the tumor volume and weight were significantly increased and decreased by GDNF and SERPINE1 deficiency, respectively." (PMID 39337713, 2024). "Using MCF-7 xenografts, it was additionally shown that in vivo GDNF expression was specific to tumor-associated fibroblasts, and negligible in primary tumor cells." (PMID 36918928, 2023). "In PDAC, activated and recruited tumor-associated macrophages at the tumor invasion site secrete high levels of GDNF." (PMID 38099290, 2023). "In the invasive margin, GFRA1 was identified as a pivotal molecule involved in cellular survival during liver metastasis formation, and we found that its oncogenic role depends on tumor associated macrophage (TAM)-derived GDNF." (PMID 36808605, 2023). "In mice, targeted transgenic overexpression of GDNF in spermatogonia is associated with accumulation of Aundiff and formation of cell clusters resembling seminomatous tumours." (PMID 37564373, 2023). "Upregulation of RET and GDNF is associated with increased expression of matrix degrading metalloproteinases that facilitate the invasion of tumor cells into the perineural space." (PMID 30666215, 2018). "As for drug response, gene GDNF is associated with cellular targets of sorafenib, the first oral multikinase inhibitor that targets Raf and affects tumor signaling and the tumor vasculature." (PMID 29299153, 2017). "Finally, GDNF has been recently implicated in tumour biology, underscoring its multifaceted role at the interface between beneficial and detrimental effects." (PMID 40642294, 2025). "Furthermore, reports have indicated that the synergy of GDNF overexpression and hypersecretion of interleukins trigger the polarization of tumor-associated macrophages into M2 microglia." (PMID 35392088, 2022). "Interestingly, perineural macrophages also express GDNF and tumor associated macrophages (TAMs) express more GDNF than resting macrophages." (PMID 31248001, 2019). "Testosterone regulates macrophage recruitment and GDNF upregulation to protect the brain cells and microglia against apoptosis without significantly affecting the inflammation state due to macrophage polarization and tumor hallmark that significantly reduces cancer cell phagocytosis." (PMID 37833789, 2023). "Additionally, as a member of the transforming growth factor beta (TGF-β) superfamily, GDNF can regulate and reprogramme macrophages into tumor-associated macrophages (TAM) in the tumor microenvironment characterized by hypersecretion of chemokines as shown in the differential gene expression." (PMID 37833789, 2023). "Peritumoral regions are implicated in tumor invasion and multiple studies have demonstrated a role of astrocytes in promoting tumor migration in different ways: by expressing the chemoattractant factor GDNF, by releasing MMPs or by inducing MMPs upregulation in tumor cells." (PMID 34690699, 2021). "CBP then acetylates histone H3 at both the enhancer and the transcription start site of the GDNF gene, facilitating the transcriptional activation of GDNF, and promoting tumor cell survival and proliferation." (PMID 41566325, 2026). "GDNF activation subsequently induces chemotactic migration of tumor cells through the PI3K/AKT and MAPK signaling pathways." (PMID 41583906, 2026). "This platform enables precise 3D mapping of tumor–nerve interfaces, with implications for identifying neurotrophic signaling pathways (e.g., GDNF/Rearranged during Transfection (RET)) and screening therapeutics targeting neural recruitment in PC models." (PMID 40243726, 2025).